STXBP3 (syntaxin binding protein 3)
Description:
Together with STX4 and VAMP2, may play a role in insulin-dependent movement of GLUT4 and in docking/fusion of intracellular GLUT4-containing vesicles with the cell surface in adipocytes.
Synonyms: PSP; Unc-18C; MUNC18-3; MUNC18C
Tractability: Antibody: UniProt places it where antibodies can reach, with high confidence; its Gene Ontology location is reachable by antibodies, with high confidence. PROTAC: ubiquitination databases record sites on it; its protein half-life has been measured.
Gene: Protein-coding gene on chromosome 1 (108,746,634 to 108,809,525, forward strand). Ensembl gene ENSG00000116266.
Subcellular location: Cytoplasm, cytosol; Cell membrane
Subcellular location (Human Protein Atlas): Nucleoplasm; Cytosol
Pathways (Reactome):
Hemostasis: Disinhibition of SNARE formation
Vesicle-mediated transport: Translocation of SLC2A4 (GLUT4) to the plasma membrane
Gene Ontology:
Molecular function: protein binding; syntaxin binding; syntaxin-1 binding; protein-containing complex binding; SNARE binding
Biological process: negative regulation of calcium ion-dependent exocytosis; neutrophil degranulation; platelet aggregation; presynaptic dense core vesicle exocytosis; immune response; negative regulation of transport; regulated exocytosis; response to stress; vesicle-mediated transport
Cellular component: cytosol; extracellular exosome; plasma membrane; platelet alpha granule; specific granule; tertiary granule; secretory granule; apical plasma membrane; basolateral plasma membrane; phagocytic vesicle; presynapse
Genetic constraint (gnomAD): Loss-of-function variants: 24 observed, 43.62 expected, observed/expected ratio (o/e) 0.55, 90% interval 0.4 to 0.77. The upper end of that interval is the gene's LOEUF score, 0.77, which puts it in group 3 of 6, group 1 being the genes least tolerant of losing a copy. Missense variants: 384 observed, 449.24 expected, observed/expected ratio (o/e) 0.85, 90% interval 0.79 to 0.93. Synonymous variants: 142 observed, 155.17 expected, observed/expected ratio (o/e) 0.92, 90% interval 0.8 to 1.05.
Homologues: Orthologues: chimpanzee STXBP3 (99% identical), macaque STXBP3 (99% identical), dog STXBP3 (95% identical), mouse Stxbp3 (92% identical), rat Stxbp3 (91% identical), rabbit STXBP3 (91% identical), guinea pig STXBP3 (89% identical), pig STXBP3 (87% identical), tropical clawed frog stxbp3 (68% identical), zebrafish stxbp3 (59% identical), Caenorhabditis elegans uncp-18 (30% identical). Paralogues in human: STXBP2 (47% identical), VPS45 (21% identical), SCFD1 (21% identical), SCFD2 (17% identical), VPS33A (16% identical), VPS33B (14% identical).
Diseases named in the same sentence as STXBP3 in open-access papers:
STXBP3 is named in the same sentence as 20 diseases in open-access papers, as found by Europe PMC text mining. Sharing a sentence is not in itself a finding about the gene and the disease. The quoted sentences say what the papers report.
Insulin resistance (5 papers, 2008 to 2022). Increased resistance towards insulin, that is, diminished effectiveness of insulin in reducing blood glucose levels. "Syntaxin‐binding protein 3 (STXBP3) is involved in fatty acid‐induced insulin resistance in skeletal muscle cells." (PMID 33090721, 2020).
hearing loss (2 papers, 2025). "In this case report, we present a novel patient diagnosed with STXBP3-associated hearing loss and VEO-IBD." (PMID 40575033, 2025). "Additionally, the STXBP3 gene is involved in platelet activation and secretion; its significance in sensorineural hearing loss and immune disorders has been established." (PMID 40282202, 2025).
chronic lymphocytic leukemia (1 paper, 2020). "In chronic lymphocytic leukemia, lipoprotein lipase can cooperate with STXBP3 to promote chronic lymphocytic leukemia cells apoptosis." (PMID 33090721, 2020).
COVID-19 (1 paper, 2022). A disease caused by infection with severe acute respiratory syndrome coronavirus 2. "Eight genes associated with platelet activation and pro-thrombosis were upregulated in COVID-19 patients: MPIG6B, HBB, HPSE, CD40LG, STXBP3, CLEC1B, TFPI and GNAS." (PMID 35477940, 2022).
insulin dependent diabetes mellitus (1 paper, 2013). "STXBP3 and CLCC1 genes on chromosome 1 have been linked to insulin dependent diabetes mellitus." (PMID 23741398, 2013).
STXBP3 also shares sentences with these, for which no sentence is quoted: Obesity (4 papers); arthrogryposis (1); cancer (1); congenital neutropenia (1); Glucose intolerance (1); head and neck cancer (1); Hearing impairment (1); immune disorders (1); infection (1); inflammatory bowel disease (1); morbid obesity (1); nephrotic syndrome (1); polycystic ovary syndrome (1); prediabetes (1); type 2 diabetes (1).